CD4 (CD4 molecule)
Diseases named in the same sentence as CD4 in open-access papers (continued):
Sharing a sentence is not in itself a finding about the gene and the disease.
AIDS (continued). "Patients were analyzed according to gender, age at index date, medical insurance type, comorbidities, depression, HIV/AIDS disease burden as indicated by HIV-RNA viral load and CD4, and laboratory variables." (PMID 33417621, 2021). "In this study, the competing risk model was used to explore the association between time from HIV diagnosis to antiretroviral therapy initiation and AIDS-related mortality in HIV/AIDS patients with high and low CD4+ cell counts." (PMID 34592916, 2021). "Median age at delivery was 29 (IQR 24, 34) years, median CD4 at delivery was 396 (IQR 250, 581) cells/μL and 107 (18%) women had an AIDS‐defining event prior to their first pregnancy outcome." (PMID 34021715, 2021). "On the other hand, due to the nature of HIV/AIDS, patients in the initially ineligible group will progress to ART eligibility over time, as their CD4 counts decline, thus attenuating the estimated effect." (PMID 34282184, 2021). "Acquired immunodeficiency syndrome (AIDS) is the last stage of HIV infection, diagnosed when CD4 cell count is less than 200 cells/mm3." (PMID 33227918, 2020). "Human CD4+ T cells are the major target for HIV infection; thus, a mouse model with human CD4+ T cells provides a platform for modeling HIV/AIDS." (PMID 32276640, 2020). "Studies suggest a positive effect of chronic HPgV-1 infection in HIV-infected patients, in which data show a higher CD4+ T-cell count, lower HIV viral load and inflammatory markers, and delayed progression to AIDS." (PMID 32369533, 2020). "More strikingly, progression to AIDS and other clinical outcomes can also occur in the presence of undetectable HIV replication and high CD4 T-cell counts." (PMID 32698654, 2020). "In Switzerland, for example, lower cluster-of-differentiation-4-expressing T cells (CD4 T cells) and advanced HIV/AIDS stage were related to higher suicide rate among PLHIV." (PMID 32448151, 2020). "The decentralization process of HIV management in Morocco is based on the creation of HIV/AIDS management activity in hospitals as well as the deployment of the HIV tests including diagnosis tests, viral load and CD4 count testing, in the hospital laboratory." (PMID 32522235, 2020). "However, CD4+ T cell numbers recover after acute infection but decrease in the course of years, ultimately leading to the development of the acquired immunodeficiency syndrome (AIDS) which is characterized by low T cell counts in the blood and the occurrence of rare opportunistic diseases." (PMID 33072074, 2020). "Using this method, one cannot only estimate the incidence of HIV infections but also the diagnosis rates at different CD4 stages and during different time intervals, providing insightful information to comprehensively evaluate the epidemiology of HIV/AIDS." (PMID 31964392, 2020). "In univariate analysis, renal impairment was more prevalent among older HIV/AIDS patients; those had higher WHO stage and baseline CD4 count less than 200 cells/mm3." (PMID 32382572, 2020). "CD4 cell count played an important role in the care and management of opportunistic infections in HIV/AIDS." (PMID 33883764, 2020). "The use of such device that simultaneously determines AbsCD4, CD4% and Hb levels from capillary and/or venous blood would simplify the routine monitoring of patients with HIV/AIDS and be particularly beneficial in resource-constrained settings." (PMID 33177659, 2020). "In the era of universal treatment of all at any CD4 level, 83% of YLHIV registered on the Thai National AIDS Program initiated ART." (PMID 32869537, 2020). "The endpoints in our study were defined by one of the three criteria, including an absolute CD4+ T cell count of <350 cells/μl, initiation of long-term ART, and progression to AIDS and death." (PMID 33072082, 2020). "This explains right away why the number of CD4 T cells, Tss, slowly decreases over the course of HIV infection, leading to AIDS." (PMID 33142907, 2020).
AIDS (continued). "Expression of PD-1 is enhanced on both CD4+ and CD8+ T cells in peripheral blood of patients with HIV/AIDS compared with healthy controls and that expression of PD-1 by Tregs directly correlates with disease progression." (PMID 32891157, 2020). "Back-calculation methods can be divided into three subgroups according to the data used: (i) AIDS diagnosis data only, (ii) both HIV and AIDS diagnosis data, and (iii) HIV/AIDS diagnosis data as well as CD4+ T-cell counts at diagnosis." (PMID 31964392, 2020). "Combination antiretroviral treatment (cART) suppress viral replication and restores CD4+ T-cell counts in the majority of PWH and has reduced AIDS-related morbidity and mortality." (PMID 33117394, 2020). "We were unable to stratify HIV co-infected patients by CSF HIV viral load or CD4 count, but all were classified as WHO AIDS Stage 3 with advanced disease." (PMID 33363056, 2020). "The required data are, at the moment, divided into four different categories: (i) epidemiological data including AIDS diagnoses and HIV diagnoses, (ii) CD4 T-cell counts at diagnosis, (iii) prevalence data, and (iv) biomarker testing data." (PMID 31964392, 2020). "Antiretroviral therapy (ART) has markedly increased CD4 counts in HIV-infected patients and reduced AIDS-related morbidity and mortality." (PMID 32793212, 2020). "In the intestinal mucosa of patients with HIV/AIDS having CMV colitis, 3.1% ± 3% of the total lymphocytes were CD4+." (PMID 32891157, 2020). "These are explained by 67 HIV/AIDS patients with tuberculosis infection; 82% were in WHO clinical stage III and IV, 73% were ambulatory and bedridden, and 55% had CD4 counts of less than 100 cells/mm3 at baseline." (PMID 32758247, 2020). "Furthermore, differences found in the CHI groups could be influenced by older age and the national guidelines at the moment of the study (2013–2014) that recommended ART initiation in patients with CD4 T-cell counts ≤350 cells/mm3 or presenting with an AIDS-defining event." (PMID 33519823, 2020). "Our study also found strong associations between both the most recent CD4+ T cell count and the CD4+:CD8+ T cell ratio and the development of a new AIDS event in both univariable and multivariable models." (PMID 32664736, 2020). "There was a statistically significant relationship between CD4 cell counts, oral hygiene, antibiotic usage, pregnancy and the prevalence of oral candidiasis in HIV/AIDS patients in this study." (PMID 32774600, 2020). "This is in line with previous data indicating that women on ART show a consistently better CD4+ T cell recovery than men21, although in some cases they may have greater levels of immune activation and inflammatory activity and a faster progression to AIDS than men22." (PMID 32094387, 2020). "Most participants correctly agreed that HIV infects and damages the CD4 cells (79.4%, n = 259) and that HIV develops into AIDS (81.6%, n = 266)." (PMID 31296188, 2019). "All 7 cases with Cryptococcal meningitis were immunocompromised (5 with Acquired Immune Deficiency Syndrome (AIDS)), 1 with lupus with CD4 count of 75 yet but negative for Human Immunodeficiency Virus, and 1 with stage IV Hodgkin’s Lymphoma with pancytopenia), which likely increased mortality." (PMID 31382892, 2019). "HIV infection progresses to develop acquired immunodeficiency disease (AIDS), which is an immuno-compromised condition, suppressing cell-mediated immunity, HIV infected or uninfected decreased CD4+ T-cell count and weakening of the immune system." (PMID 32038627, 2019). "The major aim of this study was to assess and compare the use of the time-dependent variables; CD4 cell count and viral load level, in analysing HIV/AIDS progression on patients receiving antiretroviral therapy." (PMID 30770728, 2019). "We defined “timely presentation” (TP) as CD4 > 499 cells/μL, late presentation (LP) as CD4 count <350 cells/μL and advanced HIV disease (AIDS) as <200 cells/μL, all at enrolment." (PMID 30941891, 2019).
AIDS (continued). "Taken together, whereas FcγRIIA expression in CD4+ T cells becomes a marker for HIV infection, the involvement of FcγRIIA+ CD4+ T cells in AIDS remains to be elucidated." (PMID 31057544, 2019). "Sociodemographic (gender, age, relationship status, education, employment) and clinical variables (CD4 count assessed via self-report, HIV/AIDS status, time since HIV diagnosis and antiretroviral treatment duration) were also obtained." (PMID 30097904, 2019). "Despite these limitations, our study adds to the HIV/AIDS literature by examining the possible trajectories of affect among PLWH and revealing the relationship between these trajectories and both gender and CD4 count changes." (PMID 30097904, 2019). "This low ratio indicates a disproportion of T helper (CD4) and T suppressor (CD8) lymphocytes, as observed in patients with severe immunosuppression, such as in AIDS patients." (PMID 31350973, 2019). "Prompt CD4 testing is a critical step for successful HIV treatment, making it vital to reducing the rates of HIV/AIDS in this region." (PMID 30998710, 2019). "Individual-level surveillance data for 1,077,295 cases (HIV/AIDS diagnoses, ART dispensations, CD4 counts and HIV/AIDS-related deaths) were used to calibrate the model using Bayesian inference." (PMID 30772250, 2019). "CD4 < 350 cells/μL predicted genotype-specific hrHPV persistence (adjusted OR 4.36 (95%CI: 1.18–16.04)) and ≥ HSIL was predicted by prior AIDS (adjusted OR 8.55 (95% CI 1.21–60.28))." (PMID 31438877, 2019). "Model parameters are estimated from a combination of historical surveillance data on newly reported HIV cases, mean CD4+ at HIV diagnosis and estimates of AIDS-related deaths from vital registration systems." (PMID 31385865, 2019). "In the Kuala Lumpur study only AIDS patients admitted to the hospital were included, whereas in Bangkok 11 HIV positive patients, were included (average CD4 count of 74.7 ± 134.21 cells/mm3)." (PMID 31364950, 2019). "CD4 cell count and viral load (HIV RNA) count are the laboratory markers that are regularly used for HIV/AIDS patient management in addition to predicting disease progression and/or treatment outcomes." (PMID 30770728, 2019). "Although antiretroviral regimens were freely provided to HIV/AIDS patients in China based on NFATP, the time when to initiate ART was updated from CD4 <200cells/ul to any CD4 cells levels, which reduced the incidence of OIs in China." (PMID 30906778, 2019). "Most of the HIV/AIDS patients on ART were dropout in a short period due to patients separated marital status, primary education, CD4, being merchants, farmer and daily labour." (PMID 30999924, 2019). "Trends in the frequency of (A) HIV‐infection stage according to CD4 count at enrolment in 31 HIV‐care centres in 10 countries in Latin America and (B) in the frequency of AIDS at enrolment (<200 cells/μL) by country (2013 to 2017)." (PMID 30941891, 2019). "A better understanding of the mechanistic role of follicular homing CD4 and CD8 T cells during HIV/SIV infection will aid in the design of vaccines and therapeutic strategies to prevent and treat HIV/AIDS." (PMID 29928280, 2018). "We found significant apoptosis in acute HIV infection and AIDS, while patients in chronic stages of HIV infection and patients on ART had low-grade apoptotic activity of the CD4 T cells, including resting memory cells." (PMID 30254642, 2018). "Median age 28 (IQR 24.6 to 34.5) years, median CD4 + 239 (IQR 56 to 477) cells/μL; 141 (76%) were late presenters, 58 (31.2%) AIDS presenters, 53% anti HCV+." (PMID 30362663, 2018). "Participants in the Multicenter AIDS Cohort Study (MACS) with the FcγRIIa RR genotype progressed to AIDS (i.e., CD4 count <200 cells/uL) faster than participants with RH or HH genotypes." (PMID 30815637, 2018). "In HIV/AIDS group, all positive samples for CMV genome were only found in those with CD4 below 100 cells/mm3 and, interestingly, all patients with CD4 higher than 100 cells/mm3 were negative." (PMID 29997755, 2018).
AIDS (continued). "Low CD4:CD8 ratios correlate with immune activation in virally suppressed HIV-infected individuals, and have prognostic significance for AIDS-related morbidity including some viral cancers." (PMID 30315476, 2018). "In the second step, variables related to HIV infection (CD4 count, time since HIV diagnosis, duration of ARV treatment, and HIV/AIDS status) were entered." (PMID 29793544, 2018). "Improving access to CD4 testing with point-of-care testing in high-burden, resource-limited settings has played a critical role in the scale up of ART for HIV/AIDS care and linkage to treatment." (PMID 30138398, 2018). "HIV DNA was demonstrated in about 10% of the CD4 T cells obtained from acute infected patients, chronic untreated infected patients, patients on ART, and AIDS patients." (PMID 30254642, 2018). "The largest increase was obtained with the SICLOM, which represented an increase of 52.4% in reported cases, followed by SISCEL CD4 and VL (42.9%), and SINAN AIDS (16.7%)." (PMID 29668812, 2018). "Of the participants, 297 (67.5%) were knowledgeable about HIV/AIDS and its treatments; more than half, 240 (54.5%) knew about the HIV status of their partners, and 200 (45.5%) of the partners were seropositive; the CD4 count of 266 (60.5%) was < 500 mm3." (PMID 29879913, 2018). "One study from the AIDS Therapy Evaluation Project and Netherlands (ATHENA) national observational HIV cohort estimated the effect of early vs. deferred treatment on CD4+ T-cell counts reaching 800 cells/mm3 or more after 7 years of ART." (PMID 29487595, 2018). "Secondly, we explored the value of CD4/CD8 ratio in predicting NAEs including cardiovascular or cerebrovascular diseases, kidney diseases, non-AIDS malignancies and deaths." (PMID 30261902, 2018). "Progressive HIV infection leads to a massive decrease in CD4 cells, and this is one major reason for increased vulnerability to infectious diseases in advanced HIV infection and AIDS." (PMID 30186883, 2018). "The independent factors significantly associated with nutritional status among people living with HIV/AIDS were occupation, WHO clinical stage, CD4 count, tuberculosis, duration on ART, and household food security status." (PMID 29854730, 2018). "Continued availability of test reagents for CD4 count and viral load determination, and early initiation of ART to HIV/AIDS patients will alleviate the suffering of these patients." (PMID 30558571, 2018). "CD4 T cells and autologous CD8 T cells procured from AIDS patients and co-incubated revealed robust apoptotic morphology of the HIV-infected CD4 T cells with numerous apoptotic bodies." (PMID 30254642, 2018). "Two hundred and fifty patients were included: mean age 58.1 years; AIDS at diagnosis, 116 (46.4%); on cART, 246 (98.4%); HIV‐1 RNA <20 c/ml, 217 (88.2%); mean current CD4 count, 673 cells/μl; mean age at menopause, 49 years." (PMID 29671462, 2018). "We studied the incidence and probability of CD4/CD8 normalization in an adult Thai HIV cohort and explored the predictive value of the ratio for developing of non-AIDS defining events (NAEs)." (PMID 30261902, 2018). "CD4+ Treg cells lead to marked deregulation and suppression of the immune system during HIV and HCV infections, promoting progression to AIDS, the development of fibrosis and cirrhosis, and their persistence." (PMID 30400258, 2018). "Using the FIV model for AIDS lentiviral persistence, our investigations focus upon the interaction between lentivirus-activated CD4+CD25+ Treg cells and CD4+ and CD8+ target cells." (PMID 29861472, 2018). "CD4 count and HIV-1 RNA at engagement, previous AIDS and hepatitis C-coinfection predicted mortality in NAE-free persons." (PMID 28886092, 2017). "Across all participants, significant predictors of TCVF were those with perinatal HIV aged 10–14 years, African origin, pre‐ART AIDS, NNRTI‐based initial regimens, higher pre‐ART viral load and lower pre‐ART CD4." (PMID 27625109, 2017).
AIDS (continued). "The median nadir CD4+ cell count was 283 cells/μL (IQR: 162–408 cells/μL), 10% of the patients were diagnosed with AIDS before initiating ART, 28% of the patients were smokers, and the median BMI was 23.0 kg/m2 (IQR: 21.1–25.7 kg/m2)." (PMID 28061820, 2017). "Although the success of cART has dramatically reduced the incidence of AIDS-KS in HIV-infected patients, this tumour can occur in patients on cART with low or undetectable HIV load and CD4 counts greater than 300 CD4 T-cells/mm3." (PMID 28893942, 2017). "The importance of TB-HIV/AIDS treatment integration is evident as co-infected patients on both ART and CPT, and those who have a higher CD4 count are less likely to have an unsuccessful TB treatment outcome." (PMID 28693508, 2017). "A diagnosis of Kaposi’s sarcoma (KS) of the lung was confirmed by histopathologic staining and HIV/AIDS was confirmed (HIV1 PCR 70,900 copies per mL, CD4 count 26 cells/mm3)." (PMID 28320359, 2017). "During this period the Weibull models for the HIV to AIDS and AIDS to death progression were replaced by a CD4 compartment model that allowed Spectrum and EPP to respond to changing national CD4 thresholds for ART eligibility." (PMID 28532304, 2017). "This study aimed to understand HIV-positive patients’ WTP for CD4 cell counts and viral load tests as part of their HIV/AIDS disease monitoring program in Vietnam." (PMID 28199405, 2017). "According to the National AIDS Program, approximately 80% of new HIV cases have initial CD4 cell counts less than 350 cells/l and more than half have CD4 counts less than 100 cells/l by the time they initiate antiretroviral treatment." (PMID 29145519, 2017). "Determination of the CD4 absolute cell count (CD4) is widely recognized as a robust surrogate marker of the immune competence status in adolescent and adult HIV/AIDS cohorts." (PMID 29290885, 2017). "The importance of TB-HIV/AIDS treatment integration becomes evident as patients on a combination of ART and CPT, and with a higher CD4 count are more likely to have a successful TB outcome." (PMID 28693508, 2017). "Periodic population-based household-level surveys that include biologic sampling for HIV, viral load, CD4 cell counts, and ARV drug levels should also be included as a means to corroborate program data and monitor progress towards ending AIDS." (PMID 28376085, 2017). "A diagnosis of Kaposi’s sarcoma (KS) of the lung was confirmed by histopathologic staining and HIV/AIDS was confirmed (HIV1 PCR 70,900 copies/mL, CD4 count 26 cells/mm3)." (PMID 28320359, 2017). "Tertiles of both CD4:CD8 ratio and CD8 count were prognostic for AIDS-related deaths (LR P = .016 and P = .0037, respectively)." (PMID 28903507, 2017). "A major change in methods for estimating burden of HIV/AIDS for GBD 2016 was the distribution of antiretroviral therapy coverage by age, sex, and CD4 count." (PMID 28919117, 2017). "We investigated early innate defense against human immunodeficiency virus (HIV) infection and viral evasion by utilizing human CD4+ T cell cultures in vitro and a simian immunodeficiency virus (SIV) model of AIDS in vivo." (PMID 28465428, 2017). "The Pediatric Randomized Early versus Deferred Initiation in Cambodia and Thailand (PREDICT) clinical trial, which enrolled HIV-positive children aged 1–12 years, showed high AIDS-free survival in both early (CD4 15–24%) and deferred ART (CD4 <15%) groups." (PMID 29287090, 2017). "Centers for Disease Control and Prevention Class C AIDS was present in 18.8% of patients, HIV-1 RNA ≥ 100,000 copies/mL in 43.2%, CD4 count < 200 cells/mm3 in 38.2% and < 50 cells/mm3 in 10.4%, and hepatitis C virus co-infection in 18.6%." (PMID 26899539, 2016). "HIV/AIDS variables, such as CD4 T-cell count and HIV RNA level, seem to play a secondary role for the prognosis of critically ill HIV/AIDS patients." (PMID 27800179, 2016). "The controls had higher weight, height, BMI, haemoglobin levels and CD4+ cell counts than the HIV and AIDS groups." (PMID 26956496, 2016).